HIP1R (huntingtin interacting protein 1 related)
Description:
Component of clathrin-coated pits and vesicles, that may link the endocytic machinery to the actin cytoskeleton. Binds 3-phosphoinositides (via ENTH domain). May act through the ENTH domain to promote cell survival by stabilizing receptor tyrosine kinases following ligand-induced endocytosis.
Synonyms: HIP12; KIAA0655; HIP3; FLJ14000; ILWEQ
Tractability: Antibody: its Gene Ontology location is reachable by antibodies, with high confidence. PROTAC: ubiquitination databases record sites on it; its protein half-life has been measured.
Gene: Protein-coding gene on chromosome 12 (122,834,453 to 122,862,961, forward strand). Ensembl gene ENSG00000130787.
Subcellular location: Cytoplasm, perinuclear region; Endomembrane system; Cytoplasmic vesicle, clathrin-coated vesicle membrane
Subcellular location (Human Protein Atlas): Cytosol; Plasma membrane; Vesicles
Pathways (Reactome):
Vesicle-mediated transport: Clathrin-mediated endocytosis; Golgi Associated Vesicle Biogenesis
Gene Ontology:
Molecular function: actin filament binding; clathrin binding; identical protein binding; phosphatidylinositol binding; phosphatidylinositol-3,4,5-trisphosphate binding; phosphatidylinositol-3,4-bisphosphate binding; phosphatidylinositol-3,5-bisphosphate binding; phosphatidylinositol-4,5-bisphosphate binding; protein binding; protein homodimerization activity; clathrin adaptor activity; clathrin light chain binding; actin binding; phospholipid binding; protein heterodimerization activity; SH3 domain binding
Biological process: intrinsic apoptotic signaling pathway; negative regulation of actin filament polymerization; positive regulation of epidermal growth factor receptor signaling pathway; positive regulation of mitochondrial outer membrane permeabilization involved in apoptotic signaling pathway; positive regulation of platelet-derived growth factor receptor-beta signaling pathway; protein stabilization; receptor-mediated endocytosis; regulation of actin cytoskeleton organization; regulation of endocytosis; actin filament organization; clathrin coat assembly; endocytosis; regulation of apoptotic process; regulation of clathrin-dependent endocytosis; apoptotic signaling pathway; digestive system development; membrane organization; negative regulation of apoptotic process; negative regulation of Arp2/3 complex-mediated actin nucleation; positive regulation of cellular component organization; positive regulation of clathrin coat assembly; positive regulation of transport; postsynapse organization; regulation of gastric acid secretion
Cellular component: clathrin-coated vesicle; cytosol; ruffle membrane; cortical actin cytoskeleton; dendrite cytoplasm; dendritic spine; neuronal cell body; postsynaptic density; synaptic membrane; apical plasma membrane; cell cortex; clathrin-coated pit; clathrin-coated vesicle membrane; cytoskeleton; endomembrane system; glutamatergic synapse; perinuclear region of cytoplasm; postsynapse; postsynaptic endocytic zone
Genetic constraint (gnomAD): Loss-of-function variants: 135 observed, 128.14 expected, observed/expected ratio (o/e) 1.05, 90% interval 0.92 to 1.22. The synonymous counts are far from expectation, so gnomAD's model fits this gene poorly and the ratio says little. Missense variants: 1,462 observed, 1,358.8 expected, observed/expected ratio (o/e) 1.08, 90% interval 1.03 to 1.12. Synonymous variants: 698 observed, 579.26 expected, observed/expected ratio (o/e) 1.21, 90% interval 1.13 to 1.28.
Homologues: Orthologues: chimpanzee HIP1R (99% identical), macaque HIP1R (97% identical), pig HIP1R (93% identical), rat Hip1r (92% identical), mouse Hip1r (91% identical), dog HIP1R (90% identical), guinea pig HIP1R (86% identical), tropical clawed frog hip1r (73% identical), zebrafish hip1rb (62% identical), Caenorhabditis elegans hipr-1 (31% identical), Drosophila melanogaster Hip1 (30% identical), zebrafish hip1ra (15% identical), and 1 more. Paralogues in human: HIP1 (49% identical).
Diseases named in the same sentence as HIP1R in open-access papers:
HIP1R is named in the same sentence as 34 diseases in open-access papers, as found by Europe PMC text mining. Sharing a sentence is not in itself a finding about the gene and the disease. The quoted sentences say what the papers report.
Parkinson disease (5 papers, 2012 to 2026). A progressive degenerative disorder of the central nervous system characterized by loss of dopamine producing neurons in the substantia nigra and the presence of Lewy bodies in the substantia nigra and locus coeruleus. "The first large-scale meta-analysis of published genome-wide association studies (GWAS) in Parkinson’s disease (PD) identified 5 new genetic loci (ACMSD, STK39, MCCC1/LAMP3, SYT11, and CCDC62/HIP1R)." (PMID 24312176, 2013).
gastric cancer (4 papers, 2020 to 2023). A primary or metastatic malignant neoplasm involving the stomach. "A recent study reported that Huntingtin‐interacting protein 1‐related (HIP1R) functions as a tumour suppressor in gastric cancer by inducing apoptosis and suppressing migration and invasion through targeting Akt." (PMID 36811277, 2023). "In gastric cancer, HIP1R inhibited the AKT pathway and served as a tumor suppressor via promoting apoptosis and inhibiting tumor invasion." (PMID 37031178, 2023). "It has been reported that HIP1R acts as a tumour suppressor to limit cancer progression in gastric cancer and colorectal cancer." (PMID 36811277, 2023). "Huntingtin‐interacting protein 1‐related (HIP1R) has been recognized as a tumour suppressor in gastric cancer, while its biological function in PAAD remains to be elucidated." (PMID 36811277, 2023). "HIP1R induces apoptosis of gastric cancer cells, and inhibits cell proliferation, invasion, and migration." (PMID 35209947, 2022).
colorectal cancer (3 papers, 2020 to 2023). A primary or metastatic malignant neoplasm that affects the colon or rectum. "In colorectal cancer, HIP1R was reported to alter T cell‐dependent cytotoxicity by facilitating the lysosomal degradation of PD‐L1, which assists in the escape of immune surveillance of tumour cells." (PMID 36811277, 2023). "Through binding to PD-L1, HIP1R delivers PD-L1 to lysosomes via endocytosis, thereby enhancing T cell-dependent cytotoxicity in colorectal cancer." (PMID 35209947, 2022).
prostate carcinoma (3 papers, 2020 to 2023). A carcinoma that arises from epithelial cells of the prostate gland. "In vitro, HIP1R functioned as an oncogene to enhance the invasion and migration of human prostate cancer cells." (PMID 37031178, 2023). "Ectopic HIP1R expression has also been demonstrated to promote migration and invasion of less‐invasive prostate cancer cells." (PMID 32548851, 2020). "However, Rice et al26 reported that the microRNA‐23b/‐27b cluster indirectly regulated HIP1R, while ectopic expression of HIP1R increased migration and invasion in human prostate cancer cells." (PMID 32548851, 2020). "In prostate cancer, overexpression of HIP1R triggers cell migration, invasion and non-anchored growth." (PMID 35209947, 2022).
astrocytoma (2 papers, 2022 to 2025). "Compared to astrocytomas and GBM, oligodendrogliomas exhibited a significantly higher proportion of HIP1R+ tumor cells, which is also associated with the majority of oligodendrogliomas carrying the 1p19q codeletion (right)." (PMID 40264576, 2025). "High HIP1R and low vimentin levels were observed in oligodendroglioma compared to low HIP1R and high vimentin levels in astrocytoma." (PMID 36425564, 2022). "Two cytoskeletal proteins, HIP1R and vimentin, were identified as relevant markers that could distinguish between oligodendroglioma and astrocytoma." (PMID 36425564, 2022). "Given that identifying 1p/19q status is needed to distinguish between IDH mutant astrocytoma and oligodendroglioma, and the high cost of genetic testing needed to identify it, the HIP1R/vimentin/ATRX approach could serve as an easy and reliable surrogate in clinical practice." (PMID 36425564, 2022).
Huntington disease (2 papers, 2017 to 2025). Huntington disease (HD) is a rare neurodegenerative disorder of the central nervous system characterized by unwanted choreatic movements, behavioral and psychiatric disturbances and dementia. "We selected HIP1R, ATP1B1, and WDR4 to validate the proteomic results, as they are associated with Huntington’s disease, neuronal axon regeneration, and neurological disorders, respectively." (PMID 40001624, 2025). "Unlike HIP1, HIP1R protein does not interact with the huntingtin protein directly and there is no obvious evidence for its involvement in Huntington’s disease (HD)." (PMID 28663723, 2017).
lung carcinoma (2 papers, 2019 to 2020). "The aim of this study was to investigate the expression of HIP1R and confirm its predictive or prognostic roles in anti-PD-1 therapy in nonsmall cell lung cancer (NSCLC) patients." (PMID 32403421, 2020). "Although immune checkpoint inhibition is the most popular treatment for lung cancer, relationships involving HIP1R and immune checkpoint inhibitors in lung cancer have not been studied." (PMID 32403421, 2020).
oligodendroglioma (2 papers, 2022 to 2025). A well-differentiated (WHO grade II), diffusely infiltrating neuroglial tumor, typically located in the cerebral hemispheres. "We hypothesize that high expression of HIP1R and CDKN2A represents the most indolent oligodendrogliomas, which have a favorable prognosis." (PMID 40264576, 2025).
pancreatic cancer (2 papers, 2023 to 2025). "Taken together, our data showed that both DNA methylation and miR‐92a‐3p‐mediated repression of HIP1R contribute to the malignant progression of pancreatic cancer." (PMID 36811277, 2023).
Arthritis (1 paper, 2025). Inflammation of a joint. "Huntingtin-interacting protein 1-related (HIP1R) shares some function similarities with HIP1, and HIP1 regulates arthritis and RA fibroblast-like synoviocytes (FLS) invasiveness." (PMID 40214437, 2025).
diffuse large B-cell lymphoma (1 paper, 2020). "Low expression of HIP1R is associated with worse prognosis in diffuse large B‐cell lymphoma (DLBCL) patients with the treatment of rituximab‐CHOP regimens." (PMID 32548851, 2020).
expressive language disorder (1 paper, 2020). "Diseases associated with HIP1R (Huntingtin interacting protein 1 related) include expressive language disorder and cataract." (PMID 32508047, 2020).
Gait ataxia (1 paper, 2022). A type of ataxia characterized by the impairment of the ability to coordinate the movements required for normal walking. "While HIP1R has not been implicated in synaptic plasticity or the endocytosis of postsynaptic glutamate receptors before, mice lacking HIP1 display reduced LTD and suffer from progressive neurological defects culminating in tremor, gait ataxia, and premature death." (PMID 35613266, 2022).
glioblastoma (1 paper, 2021). The most malignant astrocytic tumor (WHO grade IV).
glioma (1 paper, 2025). A benign or malignant brain and spinal cord tumor that arises from glial cells (astrocytes, oligodendrocytes, ependymal cells). "Gliomas with HIP1R+ tumor cells greater than 23.6% were more likely to carry 1p19q codeletion, with an AUC of 70.6%, suggesting that the proportion of HIP1R+ tumor cells had good predictive power for 1p19q codeletion." (PMID 40264576, 2025). "Our analysis revealed that HIP1R emerged as the most influential feature, highlighting its potential role in distinguishing glioma subtypes." (PMID 40264576, 2025). "Compared with gliomas without 1p19q codeletion, the proportion of HIP1R+ tumor cells in patients with 1p19q codeletion was significantly higher." (PMID 40264576, 2025). "Finally, we selected the following seven indicators as the mIHC panel: IDHR132H, ATRX, EGFR, CDKN2A, HIP1R, GFAP (glial fibrillary acidic protein, marker of glioma cells), and DAPI (4ʹ,6‐diamidino‐2‐phenylindole, marker cell nucleus)." (PMID 40264576, 2025).
lung adenocarcinoma (1 paper, 2020). A carcinoma that arises from the lung and is characterized by the presence of malignant glandular epithelial cells. "We performed GSEA to identify gene sets associated with HIP1R mRNA expression in the TCGA mRNA data of lung adenocarcinoma and lung squamous cell carcinoma cases." (PMID 32403421, 2020). "The web-based mRNA dataset also showed that high HIP1R expression correlated with inferior overall survival in lung adenocarcinoma (p = 0.026)." (PMID 32403421, 2020). "In lung adenocarcinoma, we identified the top 20 most prominent pathways that were upregulated in the low HIP1R mRNA expression group." (PMID 32403421, 2020). "We used a Kaplan Meier plotter tool and performed survival analysis according to HIP1R mRNA expression in lung adenocarcinoma and lung squamous cell carcinoma patients." (PMID 32403421, 2020). "Third, GSEA revealed that HIP1R mRNA expression was tightly correlated with immune-related gene sets in lung adenocarcinoma." (PMID 32403421, 2020). "In addition, HIP1R mRNA expression was significantly correlated with immune-related gene sets in lung adenocarcinoma." (PMID 32403421, 2020). "GSEA revealed that low HIP1R mRNA expression was closely associated with allograft rejection, inflammatory responses, IL6-JAK-STAT3, IL2-STAT5, and interferon gamma response pathways in lung adenocarcinoma." (PMID 32403421, 2020).
lung squamous cell carcinoma (1 paper, 2020). "In lung squamous cell carcinoma, there were no statistically significant immune-related gene sets associated with HIP1R mRNA expression." (PMID 32403421, 2020).
lymph node metastasis (1 paper, 2020). "Moreover, in subgroup analysis, the AUC of HIP1R for lymph node metastasis and advanced GC stages reached 0.801 and 0.806." (PMID 32548851, 2020).
nephrolithiasis (1 paper, 2024). The presence of a calculus in the pelvis of the kidney; this is most often composed of mineral salts and proteins. "Differential expression of AXL, HIP1R, JUP, CTNNB1, and DSG2 was confirmed via PRM, suggesting their potential roles in the development and advancement of nephrolithiasis, warranting further exploration." (PMID 39114033, 2024).
non-small cell lung carcinoma (1 paper, 2023). A group of at least three distinct histological types of lung cancer, including non-small cell squamous cell carcinoma, adenocarcinoma, and large cell carcinoma. "Consistently, in non-small cell lung carcinoma, patients with higher expression of HIP1R presented worse progression-free survival and overall survival than those with lower HIP1R." (PMID 37031178, 2023).
papillary thyroid cancer (1 paper, 2022). "It is concluded that HIP1R is of significance in the proliferation of both poorly differentiated and papillary thyroid cancer cells." (PMID 35209947, 2022).
skin melanoma (1 paper, 2025). "A recent cryoET study of CME actin forces showed putative Hip1R densities in the intact human skin melanoma cell line, SK-MEL-249." (PMID 39833141, 2025).
squamous cell carcinoma (1 paper, 2020). A carcinoma arising from squamous epithelial cells. "From the TCGA dataset, HIP1R mRNA expression levels were negatively correlated with PD-L1 mRNA levels in adenocarcinoma and squamous cell carcinoma." (PMID 32403421, 2020). "HIP1R levels also correlate with a set of genes that reflect PD-L1-related immune pathways in GSEA analysis of adenocarcinoma cases; however, there were no statistically significant immune-related gene sets associated with HIP1R mRNA expression in squamous cell carcinoma." (PMID 32403421, 2020). "Patients with high HIP1R mRNA expression exhibited poor clinical outcomes in web-based mRNA data of adenocarcinoma cases; however, HIP1R mRNA expression was not correlated with OS in squamous cell carcinoma." (PMID 32403421, 2020).
thyroid cancer (1 paper, 2022). "To further explore the potential function of HIP1R in the development of thyroid cancer, we measured its expression level in thyroid cancer cell lines." (PMID 35209947, 2022). "Knockdown of HIP1R significantly inhibited proliferation of thyroid cancer cells and clathrin-dependent endocytosis." (PMID 35209947, 2022). "It is suggested that highly expressed HIP1R promotes clathrin-dependent endocytosis in thyroid cancer cells." (PMID 35209947, 2022). "Since HIP1R is essential for the clathrin-dependent endocytic process, we thereafter explored the effect of HIP1R on the endocytosis of thyroid cancer cells." (PMID 35209947, 2022). "Upregulated HIP1R in thyroid cancer cells promotes cell proliferation and mediates the endocytosis of PTEN." (PMID 35209947, 2022). "Knockdown of HIP1R downregulated intracellular PTEN in thyroid cancer cells, but upregulated membrane-binding PTEN." (PMID 35209947, 2022). "Flurbiprofen inhibits proliferation of thyroid cancer cells by interfering with the interaction between HIP1R and PTEN, thus blocking the endocytosis of PTEN." (PMID 35209947, 2022). "In the present study, HIP1R (Huntingtin Interacting Protein 1 Related) was found upregulated in thyroid cancer tissues and cell lines compared with that in the controls, while knockdown of HIP1R significantly inhibited the proliferation of thyroid cancer cells." (PMID 35209947, 2022). "Flurbiprofen may exert an anti-tumor effect on thyroid cancer by blocking the interaction between HIP1R and PTEN." (PMID 35209947, 2022). "Interestingly, knockdown of HIP1R significantly reduced the number of clathrin-coated pits (CCPs) in thyroid cancer cells." (PMID 35209947, 2022). "HIP1R expressions in thyroid cancer from the TCGA database were analyzed by UALCAN software." (PMID 35209947, 2022). "In the present study, HIP1R was upregulated in thyroid cancer tissues and cell lines." (PMID 35209947, 2022). "Moreover, the IHC score of HIP1R was significantly higher in thyroid cancer tissues than that in normal tissues." (PMID 35209947, 2022). "Notably, flurbiprofen, a commonly used analgesic, significantly inhibited the proliferation of thyroid cancer cells and interfered with the interaction between HIP1R and PTEN, thereby enhancing the binding of PTEN to cell membrane." (PMID 35209947, 2022). "We speculated that the endocytosis of PTEN in thyroid cancer cells might be specifically induced by HIP1R." (PMID 35209947, 2022). "Combined with the previous reports and present findings, we speculate that upregulated HIP1R promotes thyroid cancer cell proliferation by interacting with PTEN and further inducing clathrin-dependent endocytosis of PTEN." (PMID 35209947, 2022). "It is suggested that highly expressed HIP1R may promote the endocytosis of PTEN in thyroid cancer." (PMID 35209947, 2022). "Therefore, we speculated that overexpression of HIP1R might promote proliferation signal of thyroid cancer cells by inducing the endocytosis of PTEN." (PMID 35209947, 2022). "However, how HIP1R promoted proliferation of thyroid cancer remains unclear." (PMID 35209947, 2022). "Our study found that flurbiprofen interfered with the interaction between HIP1R and PTEN, thereby inhibiting proliferation of thyroid cancer cells via blocking the endocytosis of PTEN." (PMID 35209947, 2022). "Our results proved the interaction between HIP1R and PTEN in thyroid cancer cells, which further downregulated membrane-binding PTEN via inducing the endocytosis of PTEN." (PMID 35209947, 2022). "In addition, the interaction between HIP1R and PTEN (phosphatase and tensin homolog) was identified in thyroid cancer cells." (PMID 35209947, 2022). "So, it is worth determining whether HIP1R-involved endocytosis also depends on the reduction of membrane-binding PTEN, which, in turn, further decreases the level of membrane-binding PTEN in thyroid cancer." (PMID 35209947, 2022).